PRMT5 (protein arginine methyltransferase 5)
Diseases named in the same sentence as PRMT5 in open-access papers (continued):
Sharing a sentence is not in itself a finding about the gene and the disease.
bladder cancer (continued). "Next, we knockdown the endogenous PRMT5 protein to investigate its role on bladder cancer growth." (PMID 30713476, 2018). "Interestingly, bladder cancers only had data showing over-expression of PRMT5, while cancers of the urinary tract had only normal expression of PRMT5, although this may be due to a small sample size." (PMID 40735501, 2025). "However, how PRMT5 functions in bladder cancer, the most common malignancy of the urological system, is unknown." (PMID 30713476, 2018). "In summary, our research strongly suggests that PRMT5 is a potential epigenetic therapeutic target in bladder cancer, and that FKA can be used as a targeted inhibitor of PRMT5 for the treatment of bladder cancer." (PMID 36199122, 2022). "It's well recognized that PRMT5 contributes to malignant processing, however, its role in bladder cancer is never reported." (PMID 30713476, 2018). "Importantly, PRMT5 inhibitor opposed tumor growth and BCLXL and c-IAP1 transcription in the bladder cancer xenograft model." (PMID 30713476, 2018). "We first downloaded the mRNA expression data of normal and bladder cancer tissues from TCGA database and analyzed the mRNA expression of a total of 97 RNA splicing proteins (including SRSF family, RBM family, HNRNP family, SF3B1, PRMT5, PUF60, U2AF1, and ZRSR2) between normal and carcinoma tissues." (PMID 33117697, 2020). "Nevertheless, the role of PRMT5 in bladder cancer, to our knowledge, is never reported." (PMID 30713476, 2018).
breast tumors (12 papers, 2015 to 2025). "In certain cases, targeting direct activators such as TBL2 and PRMT5 has been explored as a potential therapeutic strategy for breast tumors, or even the complete inhibition of EGFR/PI3K/AKT and mTOR mediated pathways using natural compounds." (PMID 39950162, 2025). "Using sections of a paraffin‐embedded fresh breast tumor, we observed that upon G595 treatment, PRMT5 expression in the nucleus significantly decreased." (PMID 37458145, 2023). "In a previous study, we described that in breast tumor samples, PRMT5 showed a dual expression in the cytoplasm and the nucleus of tumor cells." (PMID 37458145, 2023). "Han and colleagues demonstrated that PRMT5 enhanced aerobic glycolysis by regulating the liver X receptor α (LXRα)/NFκBp65 pathway in breast tumor cells." (PMID 37861293, 2023). "Together, these observations indicate that PRMT5 and MEP50 mRNA levels are inversely associated with prognosis in TNBC and luminal B breast tumors." (PMID 36230689, 2022). "Lastly, we assessed nuclear PRMT5 activity by analyzing the H4R3me2s methylation mark by IHC in breast tumors and normal tissues." (PMID 36230689, 2022). "In another study, elevated levels of PRMT5 were shown to reduce the tumour‐suppressor activity of PDCD4 in primary breast tumours by methylating its N‐terminal arginine residues, resulting in reduced patient survival." (PMID 33462997, 2021). "Our results suggest that treatment with a PRMT5 inhibitor in a syngeneic mouse erbB2/neu breast tumor model shows only a slight effect on tumor growth by itself, but significantly enhanced anti-erbB2 targeted antibody therapy." (PMID 30800128, 2019). "In order to further explore the possible clinical relevance of KLF4-PRMT5 axis in tumorigenesis, we decided to examine if disrupted regulation of KLF4 by PRMT5 is a driving factor for breast tumor initiation and progression." (PMID 26420673, 2015). "Notably, PRMT5 is overexpressed in more than 50% of primary breast tumors and 70% of metastatic breast tumors, with strongest expression in TNBC." (PMID 37400460, 2023). "However, Curie and TCGA cohort analyses indicate that TNBC, luminal breast tumors, and healthy breast tissues express comparable levels of PRMT5 mRNA." (PMID 30957988, 2019). "To test whether deregulation of KLF4 protein stability by aberrant PRMT5 affects transformation of mammary gland epithelial cell or breast tumor progression, we engineered MCF10A and MCF7 cell lines with stable and inducible expression of KLF4 and KLF4-3K42." (PMID 26420673, 2015). "Interestingly, the expression of PRMT5 positively correlated with LSD1 in breast tumor specimens." (PMID 35655230, 2022). "We find that PRMT5 mRNA and protein are expressed at comparable levels in TNBC, luminal breast tumors, and healthy mammary tissues." (PMID 30957988, 2019). "To this end, we measured the protein expression levels of PRMT5 and KLF4 in human breast tumor and adjacent normal tissue by immunohistochemistry (IHC)." (PMID 26420673, 2015). "The protein levels of both PRMT5 and KLF4 are significantly higher in breast tumor tissues than that of in the adjacent normal tissues, where their expression are well correlated with the histological grade." (PMID 26420673, 2015). "To assess whether targeting PRMT5 could boost tumor immunity, we first employed the syngeneic MMTV-neu breast tumor model with EPZ004777 treatment, which is has previously been used in a mouse tumor model." (PMID 30800128, 2019).
diffuse large B-cell lymphoma (12 papers, 2020 to 2026). "PRMT5 inhibitors are mostly effective against several kinds of carcinomas, such as solid tumors and diffuse large B-cell lymphoma, as well as non-Hodgkin’s lymphoma and AML." (PMID 40869229, 2025). "Moreover, co-treatment with PRMT5 and PARP inhibitors restores antitumor activity in PARP inhibitor-resistant AML cells, while PRMT5 inhibition combined with AKT inhibitors synergistically suppresses the growth of diffuse large B-cell lymphoma." (PMID 41204384, 2025). "In diffuse large B-cell lymphoma (DLBCL), the expression of PRMT5 is increased by B-cell receptor (BCR) signaling." (PMID 34513846, 2021). "Following a B-cell receptor activation and triggering of the PI3K/AKT signaling pathway, MYC-mediated PRMT5 transcription induces cell cycle progression, increasing cell survival and proliferation in both activated B-cell (ABC) and germinal center (GC) diffuse large B-cell lymphoma (DLBCL)." (PMID 36358861, 2022). "Myc and NF-κB also upregulate PRMT5 in Eu-myc B cells, GCB (germinal center B cell-like) DLBCL (diffuse large B-cell lymphoma) tumors, and ABC (activated B cell-like) tumors." (PMID 32743345, 2020). "Thus, PRMT5 inhibition derepresses BCL6 target genes, and suppresses DLBCL (diffuse large B-cell lymphoma) proliferation." (PMID 32743345, 2020).
non-small cell lung carcinoma (12 papers, 2013 to 2025). A group of at least three distinct histological types of lung cancer, including non-small cell squamous cell carcinoma, adenocarcinoma, and large cell carcinoma. "PF-06939999, a selective SAM-competitive PRMT5 inhibitor, showed anti-proliferative activity in non-small cell lung cancer (NSCLC) cell models, primarily impacting the pathways responsible for regulating the cell cycle and alternative splicing." (PMID 39885614, 2025). "AMG 193 is an oral MTA cooperative PRMT5 inhibitor used for non-small cell lung cancer and used in combination or IV docetaxel." (PMID 40869229, 2025). "The discovery of 3039-0164 opens up new avenues for research and design optimization of PRMT5 inhibitors, which can help improve the prognosis of non-small cell lung cancer and other cancers in the clinic." (PMID 36364261, 2022). "The discovery of 3039-0164 provides precise and creative hit compounds for the design optimization of PRMT5 lead compounds in non-small cell lung cancer." (PMID 36364261, 2022). "Protein arginine methyltransferase 5 (PRMT5) is a popular anticancer target that regulates histone or nonhistone methylation and is linked to the development and poor prognosis of non-small cell lung cancer." (PMID 36364261, 2022). "We hope that our research will spark some new ideas for improving the prognosis regimen of non-small cell lung cancer patients by optimizing the PRMT5 inhibitor design and developing drug-lead compounds." (PMID 36364261, 2022). "Many recent studies have showed that PRMT5 is upregulated in A549 non-small cell lung cancer cell line." (PMID 29545752, 2018). "This study provides a novel non-SAM-competitive hit compound for developing small molecules targeting PRMT5 in non-small cell lung cancer." (PMID 29545752, 2018). "Signal transducer and activator of transcription (STAT) is kept in an activated state in non-small cell lung cancer cells (NSCLC) through PRMT5 methylation, which also controls STAT’s transcriptional activity and tumour growth and cancer stem cell maintenance support." (PMID 38760429, 2024). "In addition, circ_PRMT5 can sponge miR-498 and thus inhibit the expression of miR-498 during non-small-cell lung cancer." (PMID 35031054, 2022). "In non-small-cell lung cancer (NSCLC), an upregulation of circ-PRMT5 and a down-regulation of miR-4458 suggests that circ-PRMT5 is a ceRNA for miR-4458." (PMID 36144454, 2022). "Clinicopathological findings of tissue microarray based samples from 229 patients with non-small cell lung carcinomas (NSCLC) and 133 cases with pulmonary neuroendocrine tumors (NET) were analyzed with regard to nuclear and cytoplasmic PRMT5 expression." (PMID 24326178, 2013).
medulloblastoma (10 papers, 2019 to 2026). A malignant, invasive embryonal neoplasm arising from the cerebellum. "Stronger PRMT5 band intensity seemed associated with higher MYC expression in medulloblastoma cell lines." (PMID 31694585, 2019). "PRMT5 has also been associated with Myc-driven primary medulloblastoma tumours." (PMID 33404912, 2021). "Group 3 medulloblastoma is also associated with aberrant expression of PRMT5." (PMID 33440687, 2021). "Overexpression of protein arginine methyltransferase 5 (PRMT5) is pivotal in MYC-driven primary medulloblastoma tumors, suggesting PRMT5 as a potential therapeutic target." (PMID 42123761, 2026). "Treatment with EPZ015666 resulted in downregulation of both PRMT5 and MYC protein expression, suppression of cell growth, and induction of apoptosis in MYC-driven medulloblastoma cells associated with G1/S cell cycle arrest." (PMID 39826691, 2025). "An aberrant increase in PRMT5 level was detected in myelocytomatosis oncogene (MYC)-driven medulloblastoma cells." (PMID 39826691, 2025). "Our lab recently analyzed the localization of the PRMT5 in tumor tissues of medulloblastoma patients as well as in MYC-amplified cell lines." (PMID 38136401, 2023). "Here, we review the publicly available preclinical and clinical studies on PRMT5 targeting using small molecule inhibitors and discuss the prospects of using them in medulloblastoma therapy." (PMID 38136401, 2023). "We found that high levels of PRMT5 not only mirror MYC expression but also correlate with poor outcomes in Group 3 medulloblastoma patients." (PMID 38136401, 2023). "This physical interaction of PRMT5 and MYC implies a potential role of PRMT5 in medulloblastoma tumorigenesis." (PMID 38136401, 2023). "PRMT5 also represents a requisite driver of tumor progression in SHH-medulloblastoma and MYC-amplified medulloblastoma." (PMID 38136401, 2023). "The depletion of PRMT1 induced apoptosis in medulloblastoma cells, while treatment with PRMT5 inhibitor decreased tumor growth and increased survival in a SHH medulloblastoma mouse model." (PMID 36671446, 2022). "This study is the only of its kind to demonstrate an association between PRMT5 and MYC in medulloblastoma." (PMID 33440687, 2021). "In 491 medulloblastoma samples, PRMT5 expression was found to be significantly overexpressed on mRNA analysis compared to 9 normal cerebellar controls." (PMID 33440687, 2021). "Further study is needed to evaluate the efficacy of EPZ015666 in inhibiting medulloblastoma growth and the role of PRMT5 in medulloblastoma tumorigenesis." (PMID 33440687, 2021). "Knocking down PRMT5 in Myc-driven medulloblastoma cells led to a significant inhibition of cell growth." (PMID 33404912, 2021). "Lastly, co-immunoprecipitation from cell extracts showed the presence of PRMT5 in myc-immunoprecipitated complexes in medulloblastoma cells." (PMID 33440687, 2021). "Silencing of PRMT5 in MYCN‐overexpressing NB cells or MYC-driven medulloblastoma cells leads to a decrease in MYCN and MYC protein levels and cell growth inhibition." (PMID 33628735, 2020). "Treatment with the PRMT5 inhibitor EPZ015666 results in a decrease of MYC protein levels and medulloblastoma cell growth, which suggests that PRMT5 inhibitors are potential therapeutics for MYC- and MYCN-driven cancers." (PMID 33628735, 2020). "We further analyzed the PRMT5 expression across medulloblastoma subgroups using a cohort that has maximum number of samples with all 4 molecular subgroups." (PMID 31694585, 2019). "To further support of association between PRMT5 and MYC, we examined co-localization of these two proteins in HD-MB03 cells and a tumor specimen of a Group 3 medulloblastoma patient, using immunofluorescence-coupled with confocal microscopy." (PMID 31694585, 2019). "Using MYC-driven medulloblastoma cells, we examined the physical interaction between PRMT5 and MYC by co-immunoprecipitation and co-localization experiments." (PMID 31694585, 2019).
medulloblastoma (continued). "Knockdown of PRMT5 using siRNA in MYC-driven medulloblastoma cells significantly decreased cell growth and MYC expression." (PMID 31694585, 2019). "Expression and association between PRMT5 and MYC in primary medulloblastoma tumors were investigated using publicly available databases." (PMID 31694585, 2019). "To address the role of PRMT5 in medulloblastoma, we first accessed expression of PRMT5 across medulloblastoma subgroups including Group 3 medulloblastoma patients and high-MYC expressing medulloblastoma cell lines." (PMID 31694585, 2019). "To this end, we performed survival analyses with respect to PRMT5 expression, using 612 medulloblastoma samples from the Cavalli (763 samples) dataset." (PMID 31694585, 2019). "Given the role of PRMT5 in MYC-driven medulloblastoma cells, we further tested the therapeutic potential of targeting PRMT5 using a selective small molecule inhibitor, EPZ015666, against medulloblastoma cell lines." (PMID 31694585, 2019). "We observed that PRMT5 protein levels were significantly (p < 0.01) higher in MYC-driven medulloblastoma cell lines compared to non–MYC medulloblastoma cell lines and normal human cerebellum cells." (PMID 31694585, 2019). "In summary, we have demonstrated for the first time that PRMT5 is a critical regulator of MYC expression in MYC-amplified medulloblastomas." (PMID 31694585, 2019). "In vitro therapeutic potential of PRMT5 in medulloblastoma was also evaluated using a small molecule inhibitor, EPZ015666." (PMID 31694585, 2019). "Our survival analyses showed that high levels of PRMT5 expression correlated with poor survival of medulloblastoma patients, a pattern recapitulated in Group 3 medulloblastoma patients." (PMID 31694585, 2019). "Our results using a PRMT5 inhibitor EPZ015666 highlight the PRMT5-MYC oncogenic axis a viable therapeutic approach for MYC-driven medulloblastoma." (PMID 31694585, 2019). "We observed significantly higher expression of PRMT5 in Group 3 (MYC-driven) medulloblastoma compared to other 3 subgroups." (PMID 31694585, 2019). "Expression levels of PRMT5 protein were also examined using medulloblastoma cell lines and primary tumors by western blotting and immunohistochemistry, respectively." (PMID 31694585, 2019). "Together, the results of co-immunoprecipitation and co-localization of MYC and PRMT5 suggest that endogenous PRMT5 forms a complex with MYC in medulloblastoma cells harboring MYC amplification." (PMID 31694585, 2019). "Taken together, these results suggest that inhibiting the specific interaction of PRMT5 with MYC arrests medulloblastoma cell growth and favors apoptosis in MYC-dependent tumors." (PMID 31694585, 2019). "Our analyses using these data showed a significant overexpression of PRMT5 in medulloblastoma compared to normal cerebellum tissues." (PMID 31694585, 2019). "Our expression findings confirm that high levels of PRMT5 not only mirror MYC expression in the most aggressive medulloblastomas but also inversely correlate with poor outcomes in patients." (PMID 31694585, 2019). "Consequently, PRMT5 is emerging as a novel target for the treatment of various cancers, including medulloblastoma." (PMID 38136401, 2023). "Provided that NCCs or cancer stem cells have a great influence on medulloblastoma recurrence and tumorigenesis, there might be a role for PRMT5 in regulating the self-renewal of tumor initiation in medulloblastoma." (PMID 38136401, 2023). "PRMT5 inhibition is also being tested for medulloblastoma therapy." (PMID 33440687, 2021). "Additionally, knockdown of PRMT5 led to a reduction in MYC expression as well as a statistically significant reduction in cell growth in medulloblastoma cell lines." (PMID 33440687, 2021). "Based on these observations, we hypothesized that PRMT5 is a novel regulator of MYC expression whose inhibition may serve as a novel therapeutic strategy in MYC-driven medulloblastoma." (PMID 31694585, 2019).